HMGA1 (high mobility group AT-hook 1)
Description:
HMG-I/Y bind preferentially to the minor groove of A+T rich regions in double-stranded DNA. It is suggested that these proteins could function in nucleosome phasing and in the 3'-end processing of mRNA transcripts. They are also involved in the transcription regulation of genes containing, or in close proximity to A+T-rich regions.
Synonyms: HMGIY; HMG-R; HMGA1A
Tractability: PROTAC: UniProt records ubiquitination sites on it; ubiquitination databases record sites on it; its protein half-life has been measured.
Gene: Protein-coding gene on chromosome 6 (34,235,618 to 34,246,236, forward strand). Ensembl gene ENSG00000137309.
Subcellular location: Nucleus; Chromosome
Subcellular location (Human Protein Atlas): Nuclear membrane; Nucleoplasm; Cytosol
Pathways (Reactome):
Disease: 2-LTR circle formation; APOBEC3G mediated resistance to HIV-1 infection; Autointegration results in viral DNA circles; Integration of provirus; Integration of viral DNA into host genomic DNA; Vpr-mediated nuclear import of PICs
Cellular responses to stimuli: Formation of Senescence-Associated Heterochromatin Foci (SAHF)
Gene Ontology:
Molecular function: cis-regulatory region sequence-specific DNA binding; DNA binding; DNA binding, bending; enzyme binding; minor groove of adenine-thymine-rich DNA binding; molecular adaptor activity; molecular function activator activity; nuclear retinoic acid receptor binding; nuclear retinoid X receptor binding; peroxisome proliferator activated receptor binding; protein binding; RNA binding; transcription coactivator activity; transcription coregulator binding; chromatin binding; RNA polymerase II cis-regulatory region sequence-specific DNA binding; structural constituent of chromatin; transcription coregulator activity
Biological process: negative regulation of cell population proliferation; negative regulation of DNA-templated transcription; oncogene-induced cell senescence; positive regulation of DNA-templated transcription; intracellular signal transduction; nucleosome disassembly; positive regulation of transcription by RNA polymerase II; regulation of DNA-templated transcription; regulation of gene expression
Cellular component: focal adhesion; nuclear membrane; nucleoplasm; nucleus; senescence-associated heterochromatin focus; cytosol; RNA polymerase II transcription regulator complex; transcription regulator complex; chromatin; chromosome
Genetic constraint (gnomAD): Loss-of-function variants: 1 observed, 10.9 expected, observed/expected ratio (o/e) 0.0917, 90% interval 0.032 to 0.44. The upper end of that interval is the gene's LOEUF score, 0.44, which puts it in group 1 of 6, group 1 being the genes least tolerant of losing a copy. Missense variants: 94 observed, 125.99 expected, observed/expected ratio (o/e) 0.75, 90% interval 0.63 to 0.89. Synonymous variants: 56 observed, 49.66 expected, observed/expected ratio (o/e) 1.13, 90% interval 0.91 to 1.41.
Homologues: Orthologues: guinea pig HMGA1 (97% identical), mouse Hmga1b (97% identical), dog HMGA1 (90% identical), pig HMGA1 (84% identical), macaque HMGA1 (61% identical), rat Hmga1 (61% identical), zebrafish si:ch211-161c3.6 (42% identical), tropical clawed frog MGC147402 (34% identical).
Diseases named in the same sentence as HMGA1 in open-access papers:
HMGA1 is named in the same sentence as 227 diseases in open-access papers, as found by Europe PMC text mining. Sharing a sentence is not in itself a finding about the gene and the disease. The quoted sentences say what the papers report.
breast carcinoma (89 papers, 2003 to 2025). "Accumulating studies suggest that the overexpression of HMGA1 is associated with the pathogenicity of various tumors, including colorectal cancer, gastric cancer, and breast cancer." (PMID 39769030, 2024). "In the current study, we used UK Biobank data to examine the relationship of HMGA1 to height, risk, and prognosis of women with breast cancer." (PMID 39040191, 2024). "To systematically evaluate the association between HMGA1 expression and patient survival in breast cancer, we performed the survival curves from Kaplan–Meier plotter and bc-GenExMiner online database." (PMID 36479041, 2022). "The survival curves showed that, for thousands of breast cancer patients, higher HMGA1 mRNA levels were associated with worse OS, worse RFS, worse DMFS, and worse PPS." (PMID 36479041, 2022). "We further investigated the association of HMGA1 expression with distinct receptors and molecular pathways in breast cancer." (PMID 36479041, 2022). "The results showed that high expression of HMGA1 was associated with cell cycle transition, DNA replication, chromosomal region, protein serine/threonine kinase activity, and ATPase activity in breast cancer." (PMID 36479041, 2022). "A collection of studies recently demonstrated that high mobility group AT-hook 1 (HMGA1), which acts as a tumor promoter, is associated with several types of human cancers, including non-small cell lung cancer, breast cancer, and cervical cancer." (PMID 34887392, 2021). "CREBBP catalyzes the acetylation of HMGA1 and histone H2B, exerting a modulatory effect on HMGA1-linked transcriptional programs in breast cancer cells." (PMID 32290535, 2020). "Here, we discover FOXM1 as a novel molecular partner of HMGA1 in regulating a gene network implicated in several breast cancer hallmarks." (PMID 31311575, 2019). "In breast cancer patients, high levels of HMGA1 and CCNE2 expression are associated with the YAP/TAZ signature, supporting this connection." (PMID 26265440, 2015). "Several studies have reported that HMGA1 expression is elevated in a variety of human cancers, including breast cancer, and enhanced HMGA1 protein expression has been associated with cancer metastasis." (PMID 26265440, 2015). "In addition, the imbalance of noncoding RNAs is a cause of the higher incidence rate and mortality rate of breast cancer, which can directly target HMGA1 to the progression of cancer." (PMID 35864955, 2022). "In this study, by performing shotgun label-free quantitative proteomics and merging these data with those previously obtained by gene array (hereafter siHMGA1 data set), we determined an HMGA1-linked protein molecular signature composed of 21 factors with prognostic value in breast cancer." (PMID 26527623, 2016). "Following bioinformatic filtering for clinically relevant genes obtained using breast cancer gene expression data sets, we obtained a panel of 21 factors that we referred to as the HMGA1 reduced signature (HRS), whose expression was linked to poor prognosis in cancer." (PMID 26527623, 2016). "Growth factors and their receptors, intracellular molecules, regulators of cell cycling, and proteases, have all been shown to be altered in sporadic breast cancer, and c-Erb-B2 and HMGA1 overexpression and loss of estrogen receptors correlate with a poor prognosis." (PMID 17254320, 2007). "Furthermore, a causal role of HMGA1 in breast cancer onset and progression has been demonstrated." (PMID 31311575, 2019). "To validate the role of HMGA1 in cancer, we selected representative breast cancer cell lines to further verify HMGA1 role." (PMID 41463532, 2025). "FOXM1 also serves as a molecular partner of HMGA1 in breast cancer progression: HMGA1 binds to FOXM1 and increases its activity as a promotor of Vascular Endothelial Growth Factor (VEGFA)." (PMID 40003882, 2025). "HMGA1 promotes breast cancer angiogenesis by supporting the stability, nuclear localization, and transcriptional activity of FOXM1." (PMID 39040191, 2024).
breast carcinoma (continued). "We conclude that HMGA1 influences height, but we were unable to demonstrate that HMGA1 is related to increased incidence or poor prognosis of tall women with breast cancer." (PMID 39040191, 2024). "As a member of the HMGA family, HMGA1 has an important role in tumorigenesis and tumor progression among gastric cancer 7, breast cancer 8, colorectal cancer 9, ovarian cancer 10, thyroid cancer 11 and bladder cancer." (PMID 38706894, 2024). "High HMGA1 protein expression has been observed in all neoplastic tissues analyzed, including colon, kidney, breast carcinomas, myeloproliferative neoplasms, and so forth." (PMID 38405614, 2024). "Flow cytometry analysis showed that HMGA1 silence induced significant cell apoptosis in breast cancer cells compared with the control group." (PMID 37035211, 2023). "An elevated expression level of HMGA1 in cancer tissues and shorter patient survival time indicated the onco-promoting role of HMGA1 in breast cancer." (PMID 37035211, 2023). "For example, expression of HMGA1, which is known to promote breast cancer angiogenesis through the transcriptional activity of FOXM1, increased in a time-dependent manner." (PMID 36661191, 2023). "Increasing studies have shown that HMGA1 expression is elevated in malignant cancers including hepatocellular carcinoma, breast cancer, gastric cancer, and uterine cancer, as well as glioblastoma, and osteosarcoma." (PMID 39282156, 2023). "Downregulation of HMGA1 induces apoptosis and cell cycle arrest and inhibits cell proliferation, migration, and invasion in breast cancer." (PMID 36479041, 2022). "The correlation between HMGA1 expression and prognosis was evaluated using Kaplan–Meier plotter (KM plotter) in patients with breast cancer." (PMID 36479041, 2022). "Overexpression of high mobility group A 1 (HMGA1) in breast cancer and neuroblastoma indicates a poor prognosis." (PMID 35629376, 2022). "To confirm the role of HMGA1 in CCF formation, we examined the HMGA1 level in a variety of breast cancer cells and observed that the HMGA1 level in MM-231 and MCF-7/ADR cells was higher than that in MCF-10A and MCF-7 cells." (PMID 35163710, 2022). "Although extensive correlative evidences indicated that HMGA1 play a role in tumor metastasis, few studies have shown the direct functional relationship between HMGA1 expression and invasion/metastasis in breast cancer." (PMID 36479041, 2022). "To further examine this relationship, we analyzed the expression of both HMGA1 and stathmin in 1881 BC samples, thanks to the Gene expression-based Outcome for Breast Cancer Online (GOBO) tool, in which all clinical information of the patients is available." (PMID 35504904, 2022). "HMGA1 was important for breast cancer progression and was a critical prognostic indicator, prompting a potential therapeutic target of breast cancer." (PMID 36479041, 2022). "HMGA1 has been investigated in breast cancer (BC) and in particular in the triple-negative subtype (TNBC)." (PMID 35504904, 2022). "HMGA1 expression was obviously high in breast cancer compared with normal tissue and the adjacent tissues according to TCGA data." (PMID 36479041, 2022). "We also used bc-GenExMiner which contained molecular subtyping of 4,384 breast cancers to analyze the relationship between HMGA1 expression and clinical characteristics." (PMID 36479041, 2022). "Since then, an elevated expression of the protein or HMGA1 gene has been confirmed in many cancers of epithelial and mesenchymal origin, e.g., breast cancer, gastric cancer, lung cancer, or glioblastoma." (PMID 35805937, 2022). "Subsequent studies found that HMGA1 expression was elevated to promote the progression of malignant cancers, including breast cancer, colon cancer, and human uterine serous carcinomas." (PMID 35040749, 2022). "EZH2 can promote CCF formation in breast cancer cells, which depends on HMGA1, and the EZH2–HMGA1–USP7 complex stabilizes CCF." (PMID 35163710, 2022).
breast carcinoma (continued). "In summary, our results showed that the HMGA1 level was significantly upregulated in breast cancer tissues and closely related to clinical feature." (PMID 36479041, 2022). "Further, function analysis revealed HMGA1 was enriched in DNA replication and cell cycle pathways in breast cancer." (PMID 36479041, 2022). "To do that, we performed ChIP analysis on vehicle and CB-treated breast cancer cells using primers spanning the promoter regions of cyclin E, which is a known target of HMGA1 and showed reduced expression in CB-treated breast cancer cells." (PMID 35610507, 2022). "Multiple studies have shown elevated HMGA1 expression in malignant cancer such as breast cancer, lung cancer, colorectal cancer, and uterine cancer." (PMID 36251702, 2022). "Another study revealed that hsa_circ_0069094 knockdown inhibited breast cancer cell glycolysis and cell carcinogenesis by regulating HMGA1 through sponging miR-661." (PMID 35223093, 2022). "In breast cancer, HMGA1, EGF and TGFβ signaling pathways, HIF-1α all promoted EMT by upregulating FOXM1." (PMID 35197112, 2022). "Consistent with that, we show significantly reduced enrichment of HMGA1 on cyclin E promoter in CB-treated breast cancer cells." (PMID 35610507, 2022). "Further studies have revealed the oncogenic function of HMGA1 in colorectal cancer, gastric cancer, and breast cancer." (PMID 35040749, 2022). "For example, in invasive and metastatic breast cancer, the phosphorylation level of HMGA1 is greater than that of low invasive primary cancer." (PMID 35864955, 2022). "Here, we find that the expression of HMGA1 and of the microtubule-destabilizing protein stathmin correlates in breast cancer (BC) patients." (PMID 35504904, 2022). "Gorbounov's article mentioned that high expression of HMGA1 in breast cancer predicted poor overall survival." (PMID 36479041, 2022). "Silencing of HMGA1 inhibits the formation of 3D spheroids, reduces the malignant features of breast cancer cells, and inhibits their migration and invasion both in vitro and in vivo." (PMID 36506071, 2022). "High-mobility group A1(HMGA1) deregulated in a variety of cancers including breast cancer, lung cancer, cervical cancer, and bladder cancer." (PMID 35125116, 2022). "In view of the clinical characteristics of HMGA1 mRNA expression in breast cancer, we try to evaluate the HMGA1 protein expression in breast cancer tissues and paired adjacent nontumor tissues by immunohistochemical staining (IHC)." (PMID 36479041, 2022). "In order to reveal the function of HMGA1 in breast cancer cells, enrichment analysis was performed using the clusterProfiler R software package." (PMID 36479041, 2022). "Similar to our results, upregulation of HMGA1 has been identified in breast cancer and osteosarcoma." (PMID 34090483, 2021). "For example, HMGA1 can promote breast cancer angiogenesis via supporting the transcriptional activity of FOXM1." (PMID 33407473, 2021). "The Villanueva laboratory discovered that HMGA1 is secreted in a regulated fashion from an invasive TNBC breast cancer cell line (MD-MBA-231)." (PMID 34572547, 2021). "Unexpected but exciting results from the laboratory of one of the authors (JV) recently uncovered evidence that the High Mobility Group A1 (HMGA1) chromatin regulator is also secreted from aggressive breast cancer cell lines when cultured in vitro." (PMID 34572547, 2021). "Hmga1 is involved in promoting metastatic processes in breast cancer and it has also been found to stimulate retroviral integration." (PMID 32793490, 2020). "Further, as HMGA1 is a known oncogene in other forms of malignancy, particularly breast cancer, it would be useful to determine if this lncRNA based mechanism is common across cancer types." (PMID 33505435, 2020). "HMGA1 promotes migration in breast cancer and is targeted by let-7, while it promotes migration of bladder cancer cells (also inhibited by let-7) and of hepatocellular carcinoma cells." (PMID 31963852, 2020).
breast carcinoma (continued). "In breast cancer, both HMGA1 and HMGA2 play a role in maintaining stem cell properties to the tumor cells." (PMID 31963852, 2020). "Overexpression of HMGA1 in MCF-7 breast cancer cells increases proliferation, while its downregulation has the opposite effect; in these cells, HMGA1 upregulates several cell cycle genes like CLK-1, Cdc25A, Cdc25B, Cyclin C, JNK2, and MAPK." (PMID 31963852, 2020). "It has been shown that LINC00963 functioned as a competitive endogenous RNA for miR-214-5p/RAB14 in esophageal cancer, miR-625/ HMGA1 or miR-324-3p/ ACK1 axises in breast cancer." (PMID 32357409, 2020). "With the aim to identify new molecular partners of HMGA1 in regulating breast cancer gene networks, we performed RNA-Seq analysis of TNBC cells depleted for HMGA1 expression." (PMID 31311575, 2019). "HMGA1 is an architectural transcription factor, widely considered a master regulator of breast cancer progression." (PMID 31311575, 2019). "The first experiments using a series of antibodies against HMGA1 showed that the migration and invasion of different invasive breast cancer cells were significantly blocked." (PMID 31779212, 2019). "For all the parameters analyzed we found that breast cancer cells silenced for HMGA1 and FOXM1 reduced these parameters and, moreover, the concomitant silencing of the two factors restored normal conditions." (PMID 31311575, 2019). "Numerous pieces of evidence have shown that HMGA1 is overexpressed in neoplasms, such as colon cancer, breast cancer, pancreatic cancer, cervical cancer and liver cancer." (PMID 31340839, 2019). "In breast cancer, the highest expression of HMGA1 corresponds to the triple-negative breast cancer (TNBC) subtype." (PMID 31779212, 2019). "Recently, it has been postulated that HMGA1 increases breast cancer aggressiveness by favoring tumor angiogenesis." (PMID 31779212, 2019). "There is emerging evidence that HMGA1 is a vital tumourigenic factor in the tumours of every functional system, but most of the relevant studies are in breast cancer and colorectal cancer." (PMID 30614613, 2019). "This study reveals FOXM1 as a crucial interactor of HMGA1 and proves that their cooperative action supports breast cancer aggressiveness, by promoting tumor angiogenesis." (PMID 31311575, 2019). "(d-f) Kaplan Meier curves of RFS in a cohort of breast cancer patients stratified by HMGA1 (d), FOXM1 (e) and VEGFA (f) expression." (PMID 31311575, 2019). "Our recent publication, which describes an alternative mechanism by which extracellular HMGA1 mediates cancer migration, invasion, and metastasis in breast cancer, offers a new view on the role of HMGA1 in cancer." (PMID 31779212, 2019). "In contrast, ECs incubated with conditioned medium from breast cancer cells silenced for HMGA1 and FOXM1 formed aggregates losing the capillary-like structures." (PMID 31311575, 2019). "For example, in breast cancer, the expression of HMGA1 protein level indicates the adverse outcome of clinical prognosis." (PMID 30614613, 2019). "Several groups highlighted a prominent role of HMGA1 in breast cancer (BC) development and progression, showing its major contribution to cell motility, stemness and self-renewal, and epithelial to mesenchymal transition (EMT)." (PMID 31382504, 2019). "Very recently we demonstrated that HMGA1 is involved in modulating breast cancer cells nuclear stiffness trough a mechanism involving histone H1 and that it drives also angiogenic properties acting in cooperation with forkhead box protein M1 (FOXM1)." (PMID 31382504, 2019). "To better define HMGA1-dependent molecular networks in sustaining breast cancer aggressiveness, we analyzed global gene expression profiles after HMGA1 depletion in the MDA-MB-231 TNBC cell line." (PMID 31311575, 2019). "The study by immunofluorescence of the HMGA1 expression and localization in breast cancer cells that secrete the protein led us to detect an accumulation of HMGA1 in the cytoplasm of these cells." (PMID 31779212, 2019).